AR (androgen receptor)
Diseases named in the same sentence as AR in open-access papers (continued):
Sharing a sentence is not in itself a finding about the gene and the disease.
hypogonadotropic hypogonadism (12 papers, 2013 to 2024). Abnormal ovarian or testicular function due to insufficient hormonal stimulation from the hypothalamic-pituitary axis. "In conclusion, our study suggests that, in men affected by postsurgical hypogonadotropic hypogonadism, the shorter length of AR gene CAG tract is associated with an improved metabolic effect of TRT, independently of the effects of other concomitant pituitary-function replacement therapies." (PMID 24454369, 2013). "With regards to AR gene polymorphisms, TRT has been seen to induce greater BMD improvement in men with post-surgical hypogonadotropic hypogonadism harbouring shorter CAG tract." (PMID 35992104, 2022). "In male postsurgical hypogonadotropic hypogonadism, shorter AR gene CAG tract length seems to yield greater metabolic improvement after TRT, independently of the effects of concomitant pituitary-function replacement therapies." (PMID 24454369, 2013). "It should be finally acknowledged that the AR CAG repeat polymorphism plays a role in testosterone replacement therapy of males with hypogonadotropic hypogonadism, since shorter AR gene CAG tract length was found to yield greater metabolic improvement in response to testosterone administration." (PMID 26421011, 2015). "BPA can also bind to the androgen receptor (AR) as an antagonist, which can disrupt the hypothalamic-pituitary-testicular axis, thereby affecting gene expression and the enzymatic activity of testicular steroidogenesis, leading to hypogonadotropic hypogonadism." (PMID 36604652, 2023). "In this work we evaluated the impact of AR gene CAG polymorphism length on metabolic effects of TRT, focusing on male postsurgical hypogonadotropic hypogonadism, a condition in which this aspect has not yet been studied." (PMID 24454369, 2013).
male breast carcinoma (12 papers, 1999 to 2025). A malignant neoplasm involving the male breast. "Male breast cancer has been genetically linked with the AR gene." (PMID 27286002, 2017). "Male breast cancer is rare, and most of the tumors are androgen-receptor positive." (PMID 40347269, 2025). "Similarly, the androgen receptor plays a significant role in the process of androgen action; however, its therapeutic value in male breast cancer seems to be poorly studied." (PMID 35800434, 2022). "The androgen receptor (AR) expression and the CAG repeat length within the AR gene appear to be involved in the carcinogenesis of male breast carcinoma (MBC)." (PMID 23272232, 2012).
neuroendocrine carcinoma (12 papers, 2011 to 2025). A malignant neuroendocrine neoplasm composed of cells containing secretory granules that stain positive for NSE and chromogranin. "Hormonal therapy induces an increase in AR−CXCR2+ neuroendocrine cancer cells in prostate tumors which causes the survival of AR+ luminal cancer cells during subsequent doses of hormonal therapy." (PMID 37108425, 2023). "AR−CXCR2+ neuroendocrine cancer cells cause the formation of a tumor microenvironment, resulting in the survival of AR+ luminal cancer cells during hormone therapy." (PMID 37108425, 2023). "Some CRPCs may develop into treatment-related neuroendocrine prostate cancer (t-NEPC), which is characterized by neuroendocrine carcinoma morphology, expression of neuroendocrine markers, loss of AR expression and independence of AR signaling." (PMID 37240468, 2023). "New biomarkers and druggable targets are shaping innovative intervention strategies against high-risk localized and metastatic PCa, including AR-independent small cell-neuroendocrine carcinoma, while presenting individualized treatment opportunities through improved design and precision targeting." (PMID 35205640, 2022). "This process, often termed as t-NEPC, always involves linage plasticity which refers to a shift cellular phenotype from androgen receptor-dependent adenocarcinoma to androgen receptor-independent neuroendocrine carcinoma." (PMID 40692870, 2025). "Poorly differentiated neuroendocrine carcinoma: 35 cases were matched, 15 cases were AR positive, and nine cases were PSA positive." (PMID 33598420, 2020). "The PC3 cells we used lack endogenous AR and originate from metastatic neuroendocrine cancer." (PMID 26936218, 2016). "Neuroendocrine cancer is immunohistochemically negative for AR and positive for chromogranin A, NSE, synaptophysin, CD56 and other markers." (PMID 38305451, 2024). "In addition, these organoid models represent a series of diverse subgroups of CRPCs, including AR-dependent adenocarcinoma, AR-negative adenocarcinoma, and neuroendocrine carcinoma." (PMID 38256166, 2024). "In this study, D45354, as a typical adenocarcinoma, expressed low levels of AR and PSA, but further treatment with castration + docetaxel induced the expression of the neuroendocrine markers CGA and CYP, indicating that this model had the characteristics of neuroendocrine carcinoma." (PMID 32092044, 2020). "Histopathology of the metastasis revealed an infiltration of the liver with neuroendocrine carcinoma cells, which were positive for the neuroendocrine biomarker CD56, but negative for PSA, PSMA and androgen receptor." (PMID 31186052, 2019).
prostatic small cell neuroendocrine carcinoma (12 papers, 2013 to 2025). "The expressions of AR and PSA were both strong in patient A but occasional in patient B. Patient C was diagnosed as small cell prostate carcinoma with a strong expression of both AR and PSA." (PMID 36033483, 2022). "Initially described as a poorly differentiated adenocarcinoma, PC3 was further demonstrated to express typical features of prostatic small-cell neuroendocrine carcinoma including AR and PSA absence, neuroendocrine and CD44 marker expression, and androgen independency." (PMID 32313004, 2020). "Moreover, these cells are AR-independent (AR- and PSA-) with characteristics of prostatic small cell neuroendocrine carcinoma." (PMID 37875732, 2023). "One manifestation is the transformation from AR-positive adenocarcinomas to AR-negative small cell neuroendocrine prostate carcinomas (NEPCs)." (PMID 30669516, 2019). "The PC-3 cell line has been demonstrated to possess characteristics of prostatic small cell carcinoma and to not express AR, while this was observed in the DU145 cells, and the mRNA level of PAP was almost undetectable in the PC-3 cells." (PMID 23426586, 2013). "Both samples with primary small cell neuroendocrine carcinoma of the prostate and sarcomatoid carcinoma (post-ADT) showed no or almost undetectable expression levels of AR-Vs and AR-FL, respectively." (PMID 36139600, 2022). "Similar to reports on small cell carcinoma of the prostate with ERG rearrangements, ERG staining was positive in adenocarcinoma expressing AR but negative in carcinosarcoma lacking AR expression, supporting phenotypic transdifferentiation of cell lineage from adenocarcinoma." (PMID 40969255, 2025).
steatosis (12 papers, 2012 to 2024). Increased lipid within the cytoplasm of cells. "Here, female 5αR1-KO mice may be more susceptible to developing steatosis due to higher dependency on small amounts of DHT formed through 5αR1 for AR stimulation than males, who would be protected by their greater pool of testosterone." (PMID 27647861, 2017). "As androgen and AR-signaling are associated with the development of steatosis, AR may be associated with HCC that is related to non-alcoholic steatohepatitis." (PMID 28475115, 2017). "Androgen/androgen receptor (AR) signaling pathway plays an important role in stabilizing energy metabolism and resisting steatosis of hepatocytes and the development of NAFLD42–45." (PMID 37528093, 2023). "Also, steroid receptors such as the oestrogen receptor (ER) and the androgen receptor (AR) decrease lipid accumulation, whereas the glucocorticoid receptor promotes liver damage and steatosis." (PMID 38674815, 2024). "GR antagonism with RU486 has favorable metabolic effects on body weight and fat mass, but is likely to cause side effects by inhibiting PR and AR transcriptional activity, while the use of CORT125281 may be limited due to adverse steatosis–inducing effects in mice." (PMID 38570726, 2024). "In agreement with this, liver tissues from HDT mice expressing ARQ62L and ARE81Q showed severe steatosis, as indicated by Oil-Red staining, and prominent glycogen accumulation, as indicated by PAS staining, compared to adjacent tissues and liver tissues from the AR WT group." (PMID 38182647, 2024).
amyotrophic lateral sclerosis (11 papers, 2013 to 2024). Amyotrophic lateral sclerosis (ALS) is a neurodegenerative disease characterized by progressive muscular paralysis reflecting degeneration of motor neurons in the primary motor cortex, corticospinal tracts, brainstem and spinal cord. "In two previous studies, 2% and 3.7% of patients diagnosed with amyotrophic lateral sclerosis carried a pathogenic repeat expansion in AR." (PMID 38585669, 2024). "A pathogenic repeat expansion in AR was observed in one male patient (0.2%) diagnosed with amyotrophic lateral sclerosis." (PMID 38585669, 2024). "One male diagnosed with amyotrophic lateral sclerosis carried a pathogenic repeat expansion in AR, and his diagnosis was revised to Kennedy’s disease." (PMID 38585669, 2024). "We observed a lower frequency of repeat expansions in AR compared to previous studies on amyotrophic lateral sclerosis patients." (PMID 38585669, 2024). "Using an exome sequencing approach with ExpansionHunter, we investigated a Norwegian amyotrophic lateral sclerosis cohort for repeat expansions in AR, ATXN1, ATXN2 and HTT." (PMID 38585669, 2024). "Norwegian amyotrophic lateral sclerosis patients (n = 414) and neurologically healthy controls adjusted for age and gender (n = 713) were investigated for repeat expansions in AR, ATXN1, ATXN2 and HTT using short read exome sequencing and the ExpansionHunter software." (PMID 38585669, 2024). "Repeat expansion analyses were performed for 414 amyotrophic lateral sclerosis patients and 713 neurologically normal controls; pathogenic and intermediate-length repeat expansions in AR, ATXN2 and HTT were observed in 3.1% of the amyotrophic lateral sclerosis patients." (PMID 38585669, 2024). "In some cases, these patients are initially misdiagnosed with amyotrophic lateral sclerosis (ALS; Lou Gehrig’s disease), however, genetic testing for an expanded AR CAG repeat (n ≥ 38) confirms a diagnosis of SBMA." (PMID 23720649, 2013).
esophageal cancer (11 papers, 2016 to 2025). A primary or metastatic malignant neoplasm involving the esophagus. "An extensive investigation is warranted into the roles of T, DHT, and AR function in esophageal cancers." (PMID 41228208, 2025). "In this study, we revealed that AP-1 guides AR binding and collaborates with AR to upregulate target gene UGT2B15 expression to enhance esophageal cancer cell invasion and metastasis." (PMID 38136265, 2023). "Our findings reveal the molecular mechanisms of AR in esophageal cancer invasion and identify the AP1-directed AR transcriptional activation of UGT2B15 as a potential therapeutic target for esophageal cancer metastasis." (PMID 38136265, 2023). "Our analysis showed that following five genes were most significantly downregulated in esophageal cancer: C16orf89 (9.78E−08), AR (1.01E−07), CKB (1.17E−07), ADH1B (1.79E−07), and NCAM1 (2.15E−07)." (PMID 33828156, 2021). "Esophageal cancer cells also express other sex hormone receptors, such as androgen receptor, progesterone receptor, and so on." (PMID 32793111, 2020). "Several genes/pathways have been implicated to esophageal cancer migration, such as Cdc42, HGF/SF, Androgen receptor, RhoA, Rac-1, and Cdc42, VEGF, HER2, PLCE1, ABCG2/V-ATPase, MMS19." (PMID 28147311, 2017). "Although cellular T or DHT is normally believed to upregulate AR levels, whether this regulation occurs in esophageal cancers remains uncertain." (PMID 41228208, 2025). "AR has been shown to be an important mediator of inflammatory signals in esophageal cancer progression and overexpression of AR in vivo has been shown to promote cell migration, invasion and proliferation in esophageal cancer." (PMID 30450159, 2018). "Androgen receptor (AR) is a key mediator of inflammatory signals in esophageal cancer progression and its expression has been shown to promote cell migration, invasion and proliferation in esophageal cancer in vivo." (PMID 30450159, 2018). "In this study, by analyzing our previous AR cistromes and androgen-regulated transcriptomes, we find that AR upregulates the expression of UGT2B15 in esophageal cancer cells." (PMID 38136265, 2023). "Pharmacological inhibition of AR and AP-1 can effectively block the expression of UGT2B15, thus inhibiting the invasion and metastasis of male esophageal cancer." (PMID 38136265, 2023). "With respect to downregulated genes, C16orf89, AR, CKB, ADH1B, and NCAM1 were the leading downregulated genes in patients with esophageal cancer." (PMID 33828156, 2021). "Importantly, genetic or pharmacological inhibition of AP-1 relieves AR-mediated UGT2B15 activation, leading to esophageal cancer cell invasion inhibition." (PMID 38136265, 2023).
lymphoma (11 papers, 2013 to 2026). A malignant (clonal) proliferation of B- lymphocytes or T- lymphocytes which involves the lymph nodes, bone marrow and/or extranodal sites. "This suggests that rather estrogens formed from androgens by aromatization than androgens acting via the AR influence lymphoma progression." (PMID 26943574, 2016). "This is despite the demonstration that androgen receptor (AR) is expressed in at least some lymphoma cells." (PMID 26943574, 2016). "Whilst it has been reported that up to 70% of B cell lymphomas express AR, we are not aware of any publications reporting expression of AR variants in human lymphoma." (PMID 29145505, 2017). "This is despite reports demonstrating AR expression in both normal lymphocytes and lymphoma cells." (PMID 26943574, 2016). "However, the androgen receptor antagonist Bicalutamide did not affect lymphoma growth, suggesting no impact of androgen receptor signaling on lymphoma progression." (PMID 26943574, 2016). "Moreover, these cancer-related AR-protein complexes demonstrated predictive survival outcomes specific to CaP, and not for breast, lung, lymphoma or medulloblastoma cancers." (PMID 25409505, 2014). "Furthermore, in contrast to other lymphomas, AR appears to be hypomethylated in mantle cell lymphoma—indicating that epigenetic silencing of AR gene expression may not be present in mantle cell lymphoma." (PMID 28085048, 2017).
muscular atrophy (11 papers, 2010 to 2023). The loss of muscle tissue due to inactivity or disease. "Conversely, exceedingly long polyQ sequences in AR favor aggregation that most likely involves beta-amyloid structure and can lead to formation of toxic fibrils, causing muscular atrophy." (PMID 34986150, 2022). "A CAG expansion in AR causes spinal and bulbar muscular atrophy; an expansion in ATXN7 causes spinocerebellar ataxia type 7." (PMID 36071529, 2022). "Androgens, acting through the AR, can be neurotrophic and are important in muscle development; hence both loss of normal AR functions and gain of novel harmful functions by the polyQ AR can contribute to neurodegeneration and muscular atrophy." (PMID 23720649, 2013). "However, in a cell model of spinal and bulbar muscular atrophy, which is caused by polyglutamine (PolyQ) expansion in the androgen receptor, PA28γ had an adverse effect on androgen receptor aggregation in a proteasome-independent manner." (PMID 35714770, 2022). "In fact, androgens acting through the AR are important for muscle development suggesting that both loss of normal AR functions and gain of novel harmful functions can contribute to neurodegeneration and muscular atrophy." (PMID 32512809, 2020). "Although not acting as an anti-inflammatory agent, PNF induces the degradation of mutant androgen receptor (AR) to eliminate skeletal muscle atrophy in patients with spinal bulbar atrophy (SBMA)." (PMID 35455387, 2022). "Similarly, in a mouse model of the polyglutamine expansion disease spinal-bulbar muscular atrophy, muscle expression of mutant androgen receptor was found to be required for disease-relevant phenotypes, excepting CNS protein aggregation." (PMID 28453524, 2017). "ASC-J9 also reduced aggregate formation and polyQ AR-induced cell death in PC12 AR112Q cells, and in AR97Q transgenic mice reversed muscular atrophy, and improved motor impairment and lifespan." (PMID 23720649, 2013).
oligospermia (11 papers, 2016 to 2025). Decreased number of spermatozoa in the semen. "We observed a significant association between AR rs1378525568 TT genotype and odds of idiopathic azoospermiaor severe oligospermia compared with normal homozygote (p = 0.035, OR: 0.433, CI: 0.197-0.951)." (PMID 35958962, 2022). "ECH can block hypothalamic androgen receptor (AR) activity and increase the secretion of luteinizing hormone and testosterone, thereby increasing sperm number, to treat oligospermia." (PMID 36003498, 2022). "It should be borne in mind that similar to AR, ERs also contribute to several steps of spermatogenesis such as modulated sperm metabolism, reduced testicular size, and severe oligospermia." (PMID 35958962, 2022). "Only two men had offspring; one of these men did not have an AR mutation and had required assisted conception after sperm analysis demonstrated oligospermia, and the other, who had an AR mutation, had conceived naturally." (PMID 27403927, 2016). "That indicates oligospermia could be a result of many more complex factors and increased AR-CAG repeat length could result in severe spermatogenesis disorder." (PMID 26962784, 2016). "Another mutation at the same amino acid residue (p.P392S) was reported in two unrelated individuals with oligospermia and did not lead to alterations of AR transcriptional activity in vitro, either." (PMID 33750429, 2021).
serous ovarian cancer (11 papers, 2010 to 2024). "In this case report we present a patient with high grade serous ovarian cancer (HGSOC) with multiple relapses with excellent disease control on AR inhibition with bicalutamide." (PMID 33245722, 2020). "We also performed IHC for phospho-mTOR and phospho-AKT, another key downstream marker of PI3K activation, on slides of high-grade serous ovarian cancer tissue and scored them using the same system as for AR IHC." (PMID 34926721, 2019). "High AR expression has previously been found to be an independent favourable prognostic factor in serous ovarian carcinoma in the here studied cohort, while ER and PR expression was not prognostic, neither in the full cohort nor in subgroup analysis according to histological type." (PMID 23800114, 2013). "High-grade serous ovarian cancer (HGSOC) has abundant expression of hormone receptors, including androgen receptor (AR), estrogen receptor α (ER), and progesterone receptor (PR)." (PMID 33891016, 2021). "Our results suggest that AR expression did not impact PFS in patients with high-grade serous ovarian cancer and therefore, does not appear to be an independent prognostic factor." (PMID 34926721, 2019). "We are, however, unaware of any studies describing AR expression in fallopian tubes, from which a substantial but not yet not fully appreciated proportion of serous ovarian carcinomas are thought to arise." (PMID 20565760, 2010). "Moreover, in a recent study, matched primary and metastatic serous ovarian cancer samples did not significantly differ with respect to nuclear AR levels." (PMID 27741511, 2017).